MTOR (mechanistic target of rapamycin kinase)
Diseases named in the same sentence as MTOR in open-access papers (continued):
Sharing a sentence is not in itself a finding about the gene and the disease.
melanoma (continued). "In conclusion, our results suggest that SA and ASA might present promising anticancer effects on melanoma cells by triggering ER stress-induced apoptosis through upregulation of NO production via Akt/mTOR/AMPK-activated eNOS action." (PMID 33184378, 2020). "The effects of blocking mTOR activity on the subcellular location of TFEB have the potential to modulate the autophagy response, which has been linked to increased vesicle trafficking and chemoresistance in melanoma." (PMID 32881934, 2020). "Taken together, these results indicated that integrin/Src/YAP1 axis mediated resistance to MAPK and PI3K/mTOR dual inhibitors, which made it a promising target for the development of combinatorial regimens overcoming MAPK and PI3K/mTOR dual inhibitors–refractory melanoma patients." (PMID 35006410, 2020). "Our data showed an anticancer activity of OA against melanoma, demonstrating its ability to inhibit melanoma cell proliferation by regulating the expression of genes and related regulatory miRNAs involved in the mTOR pathway and the apoptotic process." (PMID 33071785, 2020). "Activation of mTOR signaling with Retro-Rheb transfection significantly reversed suppression of gene expression levels of glucose transporters and glycolytic enzymes in melanoma cells induced by baicalein and baicalin." (PMID 32984331, 2020). "Furthermore, other PI3K/Akt pathway mutations (such as PTEN, mTOR, PIK3R1, and NFKB1) can co-occur in melanoma with BRAF (17–20%) or NRAS (9%) mutations." (PMID 33081092, 2020). "However, treatments with baicalein and baicalin significantly suppressed the phosphorylation of mTOR and its downstream substrates p70S6K and 4E-BP1 in the melanoma cell lines, further confirming their inhibition of mTOR signaling in melanoma cells." (PMID 32984331, 2020). "In our murine melanoma model, we also found up-regulation of PI3k/Akt/mTOR pathway." (PMID 32793477, 2020). "Targeting PPT1 blocks mTOR signaling, which reduces tumor growth of melanoma in mouse models." (PMID 31117943, 2019). "Indeed, we have demonstrated that an mTOR/NF-kB inhibitor drives a significant killing of acidic anoikis resistant melanoma cells." (PMID 31275384, 2019). "Recent studies have shown that mTOR mutations usually occur in melanoma patients and show more negative therapeutic prognosis." (PMID 31508890, 2019). "Taken together, melittin could be a more efficient anticancer agent against malignant melanoma by simultaneously targeting the PI3K/AKT/mTOR and MAPK pathways." (PMID 30866426, 2019). "Another mTOR inhibitor, temsirolimus, in combination with chemotherapeutic agent temozolomide, exhibited significant decrease in tumor growth and increased apoptotic death in melanoma cells that showed resistance to BRAF inhibitor vemurafenib." (PMID 31370278, 2019). "Mutations in MTOR genes have not been fully investigated, although they are apparently frequent in melanoma patients." (PMID 30166456, 2018). "Accumulating evidence verifies that the selective inhibition of Akt/mTOR axis could suppress proliferation and invasion via enhancing autophagy in human melanoma cells." (PMID 29483938, 2018). "Likewise, the phosphoinositol-3-kinase (PI3K)/protein kinase B (AKT)/mammalian target of the rapamycin (mTOR) pathway is also involved in melanoma genesis, and its activation often leads to increased cell survival, proliferation, and motility." (PMID 30544808, 2018). "Our results suggested that SMI-4a could enhance autophagy-inducing apoptosis by inhibiting AKT/mTOR signaling pathway in melanoma cells, and G-Rh2 could enhance the effects of SMI-4a against melanoma cancer via amplifying autophagy induction." (PMID 29483938, 2018). "The results suggest that this agent has a potent anti-melanoma feature and may be very useful to synergize other anti-cancer drugs by blocking the Hh, Wnt and PI3K/mTOR signaling pathway in melanoma cells." (PMID 28212537, 2017).
melanoma (continued). "Strikingly, we reveal a strong correlation between overexpression of Phospholipase D (PLD), which increases cellular levels of phosphatidic acid, downregulation of LKB1 and enhanced activity of mTOR in malignant melanoma, thus likely contributing to the pathogenesis of malignant melanoma." (PMID 28649994, 2017). "Esomeprazole could inhibit the mTOR signaling pathway in melanoma, thus promoting tumor progression." (PMID 29050283, 2017). "Indeed, simultaneously inhibition of the MAPK and PI3K/AKT/mTOR pathways has been proposed for melanoma." (PMID 28574827, 2017). "To test this hypothesis, we investigated whether increased expression of PLD, aberrant activation of Akt and decreased LKB1 expression correlate with enhanced mTOR activity in melanoma." (PMID 28649994, 2017). "Recently, Meierjohann (2017) suggested that crosstalk between the MAPK and PI3K/AKT/mTOR pathways may be involved in the development of treatment resistance in melanoma." (PMID 28708099, 2017). "Other signaling pathways related to endocytosis, Wnt, ECM-receptor, neurotropin, Glutamatergic, insulin, protein digestion/absorption, ErbB, Gap junction, mTOR, melanoma, phosphatidylinositol, adherens junction, GnRH, Fc epsilon RI, and circadian rhythm are also significantly affected (p<0.001)." (PMID 27793049, 2016). "Taken together, these results suggest that co-targeting of MEK1/2 and PI3K/mTOR, compared to BRAF and PI3K/mTOR dual blockade, is a more effective approach to rescue susceptibility to caspase-dependent apoptosis in melanoma cells with intrinsic cross-resistant phenotype." (PMID 26678033, 2016). "Two main signaling pathways, the RAS /RAF/MEK/ERK pathway and the FAK/PI3K/Akt/mTOR pathway are activated in melanoma and may explain the progression of this cancer." (PMID 26621838, 2016). "Analysis of responsiveness to BRAF, MEK1/2 and PI3K/mTOR inhibitors in a few short term melanoma cell cultures, from patients subsequently treated with target therapy, suggested that drug susceptibility data may predict response or resistance to treatment." (PMID 26678033, 2016). "The mTOR-related autophagy was shown to be a protective mechanism for melanoma cells." (PMID 27107419, 2016). "In combination with currently used targeted therapies of the MAPK, PI3K, and mTOR pathways, pharmacological intervention of miRNAs may allow for more durable outcomes in late stage melanoma patients." (PMID 25980496, 2015). "Our overall objective was to test whether augmenting this high oxidative stress level in melanoma cells would inhibit their dependence on oncogenic PI3K/AKT/mTOR-mediated survival." (PMID 25749517, 2015). "Overall, the data presented here supports our hypothesis that increasing ROS levels in melanoma cells above the intrinsic threshold of the oxidative stress phenotype can inhibit PI3K/AKT/mTOR-mediated survival and growth." (PMID 25749517, 2015). "Thus, treatment with an mTOR inhibitor renders angiosarcomas as sensitive to MEK inhibition as melanomas having mutant BRAF, and it renders MEK inhibitor-resistant cells sensitive to MEK inhibition." (PMID 25955301, 2015). "Taking A375 advanced melanoma cells as an example, we detected and validated mutations in BRAF, FGFR2 and mTOR that could reasonably be expected to associate with Vemurafenib (BRAFi (V), hereafter), Vargatef (FGFR2i (Va)) and Everolimus (mTORi (E))." (PMID 26327537, 2015). "However, treatment with nanomolar levels of mTOR inhibitor renders these cells as sensitive to MEK inhibition as a melanoma cell line with mutant BRAF." (PMID 25955301, 2015). "Indeed, recent works demonstrated that autophagy was primarily responsible for the anti-proliferative effects of metformin in melanoma and lymphoma cells through mTOR pathway inhibition." (PMID 25867026, 2015). "Inhibitors of mTOR pathway have been developed to target melanoma and other cancers." (PMID 26204252, 2015).
melanoma (continued). "However, treatment with nanomolar levels of an mTOR inhibitor renders these cells as sensitive to MEK inhibition as melanoma with mutant BRAF." (PMID 25955301, 2015). "Furthermore, combination of ERK and PI3K/mTOR inhibition promotes cell death in resistant melanoma cells." (PMID 25538140, 2014). "It would be of interest to determine whether the influence of SPRY4-IT1 on melanocyte and melanoma proliferation involves inhibition of lipin 2 activity and/or activation of mTOR." (PMID 25344859, 2014). "Taken together, these results suggest that association of TRAIL with co-targeting of MEK and PI3K/mTOR, or with MEK blockade only, promotes effective melanoma cell death by modulating key molecules involved in regulation of both the extrinsic and intrinsic apoptosis pathways." (PMID 25275595, 2014). "The phosphatidylinositol 3-kinase/AKT/mammalian target of rapamycin (PI3K/AKT/mTOR) pathway promotes melanoma tumor growth and survival while suppressing autophagy, a catabolic process through which cells collect and recycle cellular components to sustain energy homeostasis in starvation." (PMID 23383069, 2013). "Due to the inhibitory action of iRF on melanoma proliferation, an important mediator for cell survival, mTOR, was analyzed in order to better understand the molecular mechanism by which iRF might act." (PMID 23342114, 2013). "Conversely, mutations of PTEN detected in some primary melanomas were shown to bear an UV fingerprint, which together with the fact that UV possesses a capacity to activate AKT/mTOR cascade, substantiates the involvement of AKT and mTOR in photocarcinogenesis." (PMID 23887651, 2013). "Werzoma and colleagues were able to show that either targeting phosphoinositide 3-kinase (PI-3K) or mammalian target of rapamycin (mTOR) was sufficient to induce melanoma cell apoptosis, but when dual targeted these inhibitors resulted in a synergistic suppression of cellular proliferation." (PMID 24260524, 2013). "We hypothesized that inhibition of autophagy in combination with mTOR inhibition would block this tumor survival mechanism and hence improve the cytotoxicity of mTOR inhibitors in melanoma." (PMID 23383069, 2013). "A recent report shows that PI3K/Akt pathway mediates HIF1αactivation via mTOR-mediated inhibition of PHD2 in melanoma cells, indicating that baicalein-activatedPI3K/Akt may also inhibit PHD2 in neurons." (PMID 23904909, 2013). "The dual PI3K/mTOR inhibitor NVP-BEZ235 inhibited melanoma growth regardless of BRAF mutation status." (PMID 23455493, 2012). "Furthermore addition of the MEK inhibitor AZD6244 synergized with the dual PI3K/mTOR inhibitor NVP-BEZ235 in suppressing melanoma growth." (PMID 23455493, 2012). "The expression of the PI3K/PTEN/Akt/mTOR pathway is often upregulated in melanomas." (PMID 23455493, 2012). "Overall, the alterations in major components of the MAPK, such as BRAF and NRAS mutations, and mTOR pathways, PTEN loss and AKT overexpression, seem to have substantial influence in melanoma progression, being both pathways linked to survival and chemoresistence in melanoma." (PMID 22408430, 2012). "Utilisation of the PI3K-PKB, MEK-ERK and mTOR-p70S6K signalling pathways in melanoma, as determined by phosphorylation of signalling components, varies widely across a series of cell lines, and does not directly reflect mutation of genes coding these components." (PMID 22475322, 2012). "There is evidence from the literature that mTOR signalling is active in melanoma." (PMID 19156138, 2009). "Our results indicate that rapamycin and BAY43-9006 inhibit their cognate targets in melanoma cells (mTOR and B-Raf respectively), as well as downstream effectors thought to be in other pathways, providing evidence for cellular cross-talk between the different signaling pathways studied." (PMID 16255777, 2005).
melanoma (continued). "Furthermore, studies indicate that inhibition of the PI3K/AKT/mTOR pathway enhances melanoma cell sensitivity to the chemotherapy drug temozolomide (TMZ), suggesting that combining bee venom with TMZ could lead to a more potent inhibitory effect on melanoma." (PMID 40672371, 2025). "Interestingly, the observed association between PD‐1 expression level in tumour cells and higher mitotic counts suggests a potential role of PD‐1 in promoting tumour growth, similar to what has been postulated in human melanoma where PD‐1 mediates mTOR pathway activity." (PMID 39789732, 2025). "However, there is a lack of relevant research investigating how celastrol regulates the expression of HIF-1α and the PI3K/AKT/mTOR signaling pathway to treat B16-F10 melanoma cells, and the precise mechanism involved remains unclear." (PMID 38771435, 2024). "Thus, impairing the activity of the PI3K/Akt/mTOR intracellular signaling cascade might represent a promising strategy for advancing CSC-targeted therapies for melanoma treatment." (PMID 39199632, 2024). "Additionally, some studies have shown that mTOR inhibition is attenuated in melanoma cells due to a feedback mechanism that may promote AKT activation." (PMID 38771435, 2024). "Therefore, based on the reports from the literature and our own promising results, we decided to investigate the effect of three generations of mTOR inhibitors in the combination with an inhibitor of the MAP kinase pathway (AS-703026) on the apoptosis process in melanoma cells." (PMID 37097377, 2023). "Deregulation of mTOR activity (PI3K amplification/mutation, PTEN loss of function, AKT overexpression, and S6K1, 4EBP1, and eIF4E overexpression) is observed in many types of neoplasms in humans, particularly in melanoma, and has significant effects on the progression of the disease." (PMID 36980552, 2023). "Therefore, combined targeting of RAS/MAPK and PI3K/Akt/mTOR may be beneficial for both canine and human mucosal melanomas." (PMID 36590793, 2022). "The use of mTOR inhibitors as an alternative therapeutic strategy has demonstrated some success in KIT-activated melanoma, thereby suggesting that mTOR inhibitors as a monotherapy or in combination with first-line kinase inhibitors may be effective in targeting kinase-inhibitor-resistant tumors." (PMID 36551764, 2022). "However, future work is needed to verify whether a combinatorial treatment based on concomitant NAMPT and mTOR inhibition represents a feasible strategy for targeting BRAFi/MEKi-resistant melanoma." (PMID 36077374, 2022). "Indeed, there is some evidence this might be the case and, in line with this, mutations in MTOR and several other genes of the PI3K signaling pathway have been identified in melanomas." (PMID 33549048, 2021). "Moreover, mTOR signaling plays a role in growth stimulation and cell cycle progression, and therefore its deregulation can lead to tumorigenesis, cell proliferation, angiogenesis, metastasis, and chemoresistance in various cancers including melanoma." (PMID 33916291, 2021). "It was further hypothesized that mTOR inhibitors would reduce melanoma cell glycolytic metabolism." (PMID 34895222, 2021). "Indeed, the treatment of a melanoma patient experiencing anti-PD1 induced colitis with an mTOR inhibitor (sirolimus) could dampen systemic inflammatory responses and relieve this toxicity while sparing the anti-tumorigenic effects of PD-1 blockade." (PMID 33807608, 2021). "In our experiments, the PIKfyve inhibitor YM201636 and pyridinyl imidazole inhibitors SB202190 and SB590885 all promoted nuclear localization of TFEB, indicating that the drug-induced disruption of mTOR lysosomal tethering could inhibit mTORC1 activity in melanoma cells." (PMID 32531927, 2020).
melanoma (continued). "The PI3K/AKT/mTOR pathway is an intracellular signaling pathway important in the regulation of cell proliferation, quiescence and survival during cellular stress, and when activated, provides a growth advantage, metastatic potential and angiogenesis induction in melanoma tumors." (PMID 32605090, 2020). "Regarding melanoma therapy, MTOR may be targeted by selective inhibitors." (PMID 32850962, 2020). "Similar to intrinsic PD-1 in melanoma cells, intrinsic PD-1 in liver cancer cells has been reported to mediate tumorigenesis in immunocompromised mice via regulating mTOR signaling and thus combined inhibition of PD-1 and mTOR may be a potential therapeutic strategy for melanoma and liver cancer." (PMID 33193345, 2020). "To elucidate the molecular mechanism by which Ku80 regulated melanoma cell proliferation, we examined the expression and phosphorylation of key proteins in growth regulation, and found that knockdown of Ku80 repressed the phosphorylation of mTOR, PI3K, Akt and ERK." (PMID 31023624, 2019). "Here, we demonstrate that transient and chronic acidic-adapted melanoma cells express an anoikis resistance as a new additional trait, which may be targeted by mammalian target of rapamycin (mTOR)/nuclear factor kappa-light-chain-enhancer of activated B cells (NF-kB) inhibitors." (PMID 31275384, 2019). "SMI-4a, a pharmacological inhibitor of PIM-1, could decrease cell viability, induce apoptosis, and promote Caspase 3/7 activity in both A375 and G361 melanoma cells, and SMI-4a inhibited tumor growth by inducing autophagy via down-regulating AKT/mTOR axis in melanoma cells." (PMID 29483938, 2018). "Further, the alterations in major components of the mTOR pathway like loss of function of PTEN, PI3K amplification/mutation and over-expression of S6K1, 4EBP1, eIF4E and AKT have been reported to be associated with many types of cancers, particularly in melanoma and glioblastama." (PMID 28587194, 2017). "Thus in melanoma, loss of LKB1 in PLD2 overexpressing tumours may further contribute to mTOR activation, whereas in benign neoplasia higher LKB1 level counterbalance aberrant PLD2 activation." (PMID 28649994, 2017). "Thus, we speculate that nsPEFs might improve the therapeutic effect of the mTOR inhibitor everolimus in melanoma." (PMID 28054548, 2017). "However, key questions to be answered are whether BRAF-mutated melanomas, with intrinsic resistance to BRAF and/or MEK inhibitors, also have primary cross-resistance to PI3K/mTOR inhibitors and which is the frequency of such cross-resistant phenotype." (PMID 26678033, 2016). "Therefore, we used NexrutineR, as a tool to test whether inducing ROS in an oxidative stress phenotype would disrupt survival of melanoma cells through the PI3K/AKT/mTOR pathway." (PMID 25749517, 2015). "Therefore, Bcl-2 and Bax family proteins modulate melanoma proliferation through PI3K/mTOR or MAPK signaling pathways and could effectively regulate melanoma disease and prevent tumor progression." (PMID 24647338, 2014). "This study found that melatonin combined with thapsigargin or tunicamycin directly influenced cell death of B16F10 melanoma cells via the PI3K/Akt/mTOR pathway, suggesting that melatonin combined with ER stress could be a new therapeutic strategy for effective melanoma treatment." (PMID 24647338, 2014). "Here, we treated two melanoma brain metastasis cell lines, H1_DL2, harboring a BRAFV600E mutation and PTEN loss, and H3, harboring WT (wild-type) BRAF and PTEN loss, with the MAPK (BRAF) inhibitor vemurafenib and the PI3K pathway associated mTOR inhibitor temsirolimus." (PMID 24840574, 2014). "In conclusion, this study indicated that BA and BE promoted B16-F10 cells apoptosis and autophagy, suppressed HUVEC angiogenesis, and modulated the PI3K/AKT/mTOR and MAPK signaling pathways to exert anti-melanoma effects." (PMID 41596235, 2026).